IRF2 (interferon regulatory factor 2)
Diseases named in the same sentence as IRF2 in open-access papers (continued):
Sharing a sentence is not in itself a finding about the gene and the disease.
infection (continued). "The transcription factors IRF1 and IRF2 mediate non-canonical inflammasome activation by driving the expression of CASP4 and GSDMD genes at steady state and during infection." (PMID 38106412, 2023). "IRF2, RNASEL and SP100 are all upregulated in the CD4 cells of vervet monkey but not of macaques one day post infection." (PMID 31765391, 2019). "In spleen cells, the IFN-γ expression level was up-regulated at 4 weeks after M. avium infection; however, the expression levels of IRF-1-, IRF-2- and Sca-1-, and IFN-γ-responsive genes did not increase or decrease until 4–12 weeks after infection." (PMID 29259694, 2016). "Using this system, we observed the expression of IRF-1 but not IRF-2, a repressor of CEACAM1 transcription and other target genes, 12 h after infection with an apparent peak at 24 h." (PMID 24650050, 2014). "Interferon regulatory factor-2 (IRF-2) expression did not change in the bone marrow cells, whereas it decreased in spleen cells at 4 weeks and IRF-1 expression was up-regulated in both bone marrow and spleen cells after infection." (PMID 29259694, 2016).
bacterial infections (2 papers, 2019 to 2022). "In addition, a further 12 ISGs of 380 tested ISGs including STAT1, STAT2, JAK1, IRF9, IRF2, IRF7 are key elements of IFN signaling, and classical and well-known ISGs such as ISG15, PKR, MX1, IFIT1, PML, IFI27 play key roles in viral or bacterial infections." (PMID 30717477, 2019).
lung (1 paper, 2025). "The miRNA-18a promotes lung cancercell proliferation and migration by targeting interferon regulatory factor 2(IRF2), an IRF family member, that plays a crucial role in adaptive immunity intumorigenesis." (PMID 40475735, 2025).
metabolic disorders (1 paper, 2025). "Importantly, several of these genes (e.g., IRF2, SLC38A1, CLEC2D) have been previously implicated as potential biomarkers or functional mediators in autoimmune or metabolic disorders, supporting their relevance for early detection strategies." (PMID 40740938, 2025).
IRF2 also shares sentences with these, for which no sentence is quoted: Sepsis (6 papers); inflammatory skin disease (3); atopic dermatitis (2); non-small cell lung carcinoma (2); viral myocarditis (2); alcoholism (1); arterial hypertension (1); Autoimmunity (1); breast invasive carcinoma (1); celiac disease (1); chronic hepatitis B (1); clear cell carcinoma (1); CNS tumors (1); colorectal tumors (1); diabetes (1); eczema herpeticum (1); embryonal carcinoma (1); Ewing sarcoma (1); hematological cancers (1); hematological diseases (1); leukocytosis (1); lung adenocarcinoma (1); metastatic melanoma (1); metastatic tumors (1); multiple sclerosis (1); oral squamous cell carcinoma (1); pancreatic ductal adenocarcinoma (1); polycystic ovary syndrome (1); pregnancy disorder (1); pulmonary fibrosis (1).
A further 3 diseases each share a sentence with IRF2 in 1 paper.